SPMIP3 (sperm microtubule inner protein 3)
Synonyms: C1orf100
Tractability: No criterion of Open Targets' tractability assessment is met for any kind of drug.
Gene: Protein-coding gene on chromosome 1 (244,352,635 to 244,389,663, forward strand). Ensembl gene ENSG00000173728.
Subcellular location (Human Protein Atlas): Nucleoplasm; Calyx; Cytosol; Nuclear bodies
Genetic constraint (gnomAD): Loss-of-function variants: 13 observed, 14.57 expected, observed/expected ratio (o/e) 0.89, 90% interval 0.58 to 1.42. The upper end of that interval is the gene's LOEUF score, 1.42, which puts it in group 5 of 6, group 1 being the genes least tolerant of losing a copy. Missense variants: 148 observed, 171.25 expected, observed/expected ratio (o/e) 0.86, 90% interval 0.75 to 0.99. Synonymous variants: 62 observed, 64.09 expected, observed/expected ratio (o/e) 0.97, 90% interval 0.79 to 1.2.
Homologues: Orthologues: chimpanzee SPMIP3 (99% identical), macaque SPMIP3 (95% identical), rabbit SPMIP3 (75% identical), pig SPMIP3 (73% identical), dog SPMIP3 (69% identical), guinea pig SPMIP3 (67% identical), mouse Spmip3 (67% identical), rat Spmip3 (56% identical).